MIR518A2 (microRNA 518a-2)
Synonyms: hsa-mir-518a-2; MIRN518A-2; MIRN518A2; mir-518a-2
Gene: MicroRNA gene on chromosome 19 (53,739,333 to 53,739,419, forward strand). Ensembl gene ENSG00000207699.
Gene Ontology:
Biological process: miRNA-mediated post-transcriptional gene silencing